ENSG00000288699 (novel protein)
Gene: Protein-coding gene on chromosome 9 (35,065,339 to 35,074,175, reverse strand). Ensembl gene ENSG00000288699.
Genetic constraint (gnomAD): Missense variants: 25 observed, 29.43 expected, observed/expected ratio (o/e) 0.85, 90% interval 0.62 to 1.19. Synonymous variants: 9 observed, 11.62 expected, observed/expected ratio (o/e) 0.77, 90% interval 0.47 to 1.35.